EZH2 (enhancer of zeste 2 polycomb repressive complex 2 subunit)
Diseases named in the same sentence as EZH2 in open-access papers (continued):
Sharing a sentence is not in itself a finding about the gene and the disease.
cancer (continued). "Understanding these mechanisms could provide valuable insights for enhancing the therapeutic targeting of EZH2 in cancer treatment." (PMID 40719074, 2025). "In OSCC, silencing HOTAIR led to decreased binding of EZH2 and H3K27me3 with the E‐cadherin promoter, suggesting that HOTAIR may repress the expression of E‐cadherin by recruiting EZH2 and, thereby, inhibiting cancer cell proliferation and invasion." (PMID 40231344, 2025). "Moreover, targeting EZH2 for cancer therapy is currently a highly active area of research, and various types of EZH2 inhibitors have been developed." (PMID 39982908, 2025). "Thus, while the H3K27 methyltransferase EZH2 consistently supports cancer stemness and CSC-mediated oncogenesis, the role of H3K27 demethylases such as KDM6A is highly context dependent." (PMID 40744921, 2025). "Alterations in EZH2, the catalytic subunit of PRC2, are strongly associated with various cancers." (PMID 40032852, 2025). "Obviously, multiple pathways are involved in the EZH2-promotion of cancer progression." (PMID 40028035, 2025). "Data from this study suggest that dual targeting EZH2 and HDACs may provide a promising treatment option for this aggressive cancer." (PMID 40464712, 2025). "Mechanistically, overexpression of EZH2 promotes cancer invasion and migration by directly silencing the expression of related genes that impedes cell invasion and migration such as E-cadherin, Slit homolog 2,66 and Forkhead box C167 in a variety of cancers." (PMID 40028035, 2025). "Dysregulation of EZH2 can accelerate cell proliferation and extend cell survival, which may lead to oncogenesis and cancer progression." (PMID 40115023, 2025). "Additionally, role of EZH2 in the epigenetic regulation of gene expression is recognized as a crucial element in influencing immune evasion in cancer cells." (PMID 40308579, 2025). "Additionally, it has been demonstrated that EZH2 expression by cancer cells can suppress anti-cancer immune response, diminishing CD8+ T cell infiltration in the tumor microenvironment." (PMID 41551874, 2025). "Briefly, the inhibition of EZH2 on apoptosis provides a basis for targeting EZH2 to treat cancer." (PMID 40028035, 2025). "The successful development of EZH2 inhibitors has led to active research on the mechanisms by which various HMTs function, and these studies have shown that HMTs have potential for use as crucial targets for cancer treatment." (PMID 39482529, 2024). "EZH2 expression/activity is often dysregulated in cancer, contributing to carcinogenesis and immune escape, thereby representing an important target in anti-cancer therapy." (PMID 39769907, 2024). "It is also unclear whether blocking EZH2 will have a better cancer treatment outcome in vivo, despite the promise of cancer suppression demonstrated in 2D cancer models." (PMID 37992808, 2024). "In addition, EZH2 is positively correlated with MSI‐H or TMB in pan‐cancer, indicating a greater therapeutic potential for EZH2 inhibitors as well as higher sensitivity to immunotherapy, thereby further implying the rationality of the combination approach." (PMID 38520088, 2024). "Similar to Ezh2, PLAU is also implicated in developing multiple cancer types." (PMID 38533492, 2024). "Various studies have confirmed the function of the SOX4/EZH2 axis in cancer models." (PMID 38169402, 2024). "Current research indicated that EZH2 plays a pivotal role in the progression of cancer." (PMID 40135141, 2024). "As we showed above that EZH2 modulation of cancer cell metabolism depended on the presence of ECM, we then asked whether the nature of the ECM also impacts metabolic modulation." (PMID 37992808, 2024). "Thus, our findings highlight the importance of the presence and nature of ECM in studying the function of EZH2 and its inhibitors’ effects in cancer cells for modeling the in vivo outcomes." (PMID 37992808, 2024).
cancer (continued). "Based on the findings above, HIF‐1α and EZH2 may play a functionally complementary carcinogenic role in cancer development and may account for single‐drug resistance and poor therapeutic efficacy." (PMID 38072662, 2024). "Furthermore, we found that the Enhancer of Zeste Homolog 2 (EZH2), a well-known epigenetic regulator, plays a pivotal role in modulating PVRL3 levels in TNBC cancer cell lines expressing EZH2 along with high levels of PVRL3." (PMID 39120328, 2024). "Thus, targeting the direct expression of the EZH2 protein emerges as a promising approach for inhibiting cancer growth in MCV-positive MCC patients." (PMID 38534385, 2024). "It has been reported that EZH2 is highly expressed in various cancer types and mediates epigenetic silencing by catalyzing the heterochromatin histone mark H3K27me3 at specific loci, which in turn induces changes in gene expression leading to abnormal biological functions." (PMID 38473229, 2024). "However, resistance to EZH2 inhibitors are observed in ARID1A mutant cancers and recent data suggest that the switch of the SWI/SNF catalytic subunits from SMARCA4 to SMARCA2 underlies the acquired resistance to EZH2 inhibitors." (PMID 39471843, 2024). "Along with EZH2, other KMTs are dysregulated in cancer and other diseases." (PMID 38914477, 2024). "Among other causes, p16 overexpression in cancer cells has been related to RB1 loss of function, which prevents the CDKN2A locus silencing by Polycomb Repressor Complexes and trimethylation of lysine 27 on histone H3 by EZH2." (PMID 36453028, 2024). "Notably, EZH2 overexpression has been mainly described in fibrosis and cancer, showing a positive correlation with their progression." (PMID 39408226, 2024). "A few genes on chromosome 7 that may play a crucial role in the disease pathogenesis and phenotype of cancers are EZH2, KMT2A, SAMD9, SAMD9L, and CUX1." (PMID 39463522, 2024). "Targeting EZH2 emerges as an important strategy for cancer treatment and shows promising results." (PMID 38339397, 2024). "Given the role of PRC2 in gene silencing, it is no wonder that deregulation of EZH2 levels is associated with cancer development and progression, thus rendering the protein an ideal target for drug treatment." (PMID 38473745, 2024). "However, given the documented risk of inflammatory and autoimmune system complications, a deeper understanding of the interplay between EZH2 inhibitors and ICB in treating ARID1A mutated cancers remains crucial." (PMID 38893181, 2024). "Despite various studies that have proven that EZH2 can suppress apoptosis in cancer, the exact mechanisms of apoptosis suppression by EZH2 still remain unknown." (PMID 39204206, 2024). "Recent research has suggested that inhibiting EZH2 could represent a promising therapeutic strategy for various types of cancer, leading to the development of specific EZH2 inhibitors currently in clinical trials." (PMID 39120328, 2024). "Previous reports have demonstrated that the EZH2 inhibitors repressed the level of H3K27me3 and at the same time activated H3K27ac levels and subsequently abated the activation of ISGs and the effects of cancer immunotherapy." (PMID 38461299, 2024). "In addition to its well-known function as a transcriptional activator, YAP functions as a transcriptional repressor by interacting with the polycomb repressive complex member EZH2 in cancer." (PMID 38245781, 2024). "Therefore, BTYNB can be used as a reagent to target multiple pathways (C-Myc, CDC5L, EZH2, etc.)or be used in combinatorial targeting strategies to modulate the cell cycle and enhance apoptosis of cancer cells more effectively." (PMID 39534570, 2024). "Thus, our findings highlight the importance of the presence and nature of extracellular matrix in studying the function of EZH2 and its inhibitors in cancer cells for modeling the in vivo outcomes." (PMID 37992808, 2024).
cancer (continued). "Thus, the narrative surrounding SWI/SNF and cancer takes an intriguing trajectory as it intersects with EZH2 and oncogenic transcription factors." (PMID 39471843, 2024). "Novel inhibitors have been developed to block EZH2 in these cancers." (PMID 39280246, 2024). "There are several ongoing clinical trials using EZH2 inhibitors in different cancer types." (PMID 38339397, 2024). "Altogether, RRM2, CCNB1, HMMR, and EZH2 seemed to be key genes in cancer development." (PMID 39118438, 2024). "Moreover, MS147 demonstrated inhibition of cell proliferation in various cancer cells that exhibit resistance to EZH2 knockout (KO) or EED/PRC2 degraders." (PMID 38389844, 2024). "Therefore, we are dedicated to further investigating the upstream regulatory pathways of EZH2 to address the limitations of current EZH2 inhibitors and provide more effective treatment options for cancer." (PMID 39043634, 2024). "In vitro studies have demonstrated that ARID1A deficiency could sensitize cancer cell lines to PARPi, BRD4 inhibitor and EZH2 inhibitor." (PMID 39104720, 2024). "AGAP2-AS1 influenced CDKN1A transcription by interacting with EZH2 in cancer cells." (PMID 39124865, 2024). "The observed differences in EZH2's function may be attributed to variations in the cancer microenvironment." (PMID 38600608, 2024). "Our results are also consistent with other reports showing that AKT inhibition by MK2206 reduced EZH2 protein stability in several cancer cells, indicating the methylation-phosphorylation switch of EZH2 exists in many cells, but T47D is defective in this pathway." (PMID 38346162, 2024). "Further, inhibition of EZH2 in pancreatic ductal adenocarcinoma, small cell lung cancer, and cancer-associated fibroblasts upregulated the SASP without changing the numbers of senescent cells." (PMID 38949020, 2024). "Interestingly, the authors further demonstrated that high EZH2 levels led to poor survival in all four cancer types studied in a population-based setting." (PMID 38473229, 2024). "EZH2 is overexpressed in many cancer entities and correlates with a poorer prognosis." (PMID 38339397, 2024). "Brucea javanica oil has therapeutic effects on many cancers, and recent studies have shown that Brucea javanica oil can inhibit tongue squamous cell invasion and metastasis by modulating the miR/138/EZH2 pathway; However, its specific mechanism of action on OSCC has not been reported." (PMID 39871949, 2024). "We could detect upregulated genes as well (PLAU, SERPINA1, and AKT3), mainly connected to cancer development and progression and mesenchymal phenotypes, that were also responsive to EZH2 inhibition." (PMID 38672463, 2024). "A case-control study in Taiwan showed that not all EZH2 genotypes correlate with a higher susceptibility for carcinoma." (PMID 40135141, 2024). "Overall, the carcinoma tissue samples showed a high expression of EZH2 (mean expression > 60%)." (PMID 40135141, 2024). "Therefore, combining immunotherapy with targeted inhibition of EZH2 represents a promising approach for cancer treatment." (PMID 37909018, 2023). "EZH2, a histone methyltransferase in the human genome, catalyzes the lysine trimethylation of histone 3 at position 27 (H3K27me3), which leads to the silencing of its target genes involved in cell proliferation, cell differentiation, and cancer development." (PMID 36672374, 2023). "Moreover, EZH2 expression exhibited a positive relationship with CNV in numerous tumors, partially explaining the aberrant overexpression of EZH2 in most cancers." (PMID 36545914, 2023). "Our data indicate that the anti-cancer effect of EZH2 inhibition in RMS cells may partly be due to the dysregulation of cholesterol homeostasis as revealed by the RNA-seq and ChIP-seq data." (PMID 37858275, 2023). "Scientists have found that down-regulation of some miRNAs leads to up-regulation of EZH2 in cancer, therefore restoring miRNA expression might be an effective HCC therapy." (PMID 37268997, 2023).
cancer (continued). "Interestingly, the dual inhibition of EZH2 and p38 decreases cancer progression in mouse models of TNBC." (PMID 37369946, 2023). "Regarding the s3 subtype, there is high interest in targeting EZH2 for cancer therapy." (PMID 36731467, 2023). "These PROTACs link a selective EZH2 inhibitor to the CRBN ligand 4-hydroxythalidomide and can degrade the proteasome of the PRC2 subunit in multiple cancer cell types, including EZH2, EED, SUZ12, and Retinoblastoma-binding protein 48 that can completely block EZH2." (PMID 36770884, 2023). "Several EZH2 inhibitors are currently undergoing clinical trials for the treatment of cancers." (PMID 37461108, 2023). "EZH2 itself is a common target of deregulated expression in cancers." (PMID 37240229, 2023). "Interestingly, the Ezh2 inhibitor has been used as an anti-cancer drug (Tazemetostat) to promote the tumoricidal immune response and is currently approved for the treatment of follicular lymphoma and epithelioid sarcoma." (PMID 36982437, 2023). "Furthermore, greater EZH2 mRNA expression has been found in HNSCC patients and is associated with stages of cancer and relapse, implying a role for EZH2 in HNSCC progression." (PMID 38129938, 2023). "Additionally, EZH2 has non‐histone methylase catalytic activity, which also contributes to cancer progression." (PMID 38050190, 2023). "Targeting EMT inducers, such as EZH2 and BMI-1, may prevent cancer metastasis and improve the effectiveness of anti-cancer drugs." (PMID 36829176, 2023). "All the studies above reveal that EZH2 may serve as a potential pan-cancer marker for prognosis prediction and improved treatment." (PMID 36545914, 2023). "In addition, high expression of EZH2 was observed in the human liver multidrug-resistant cancer cell line Bel/FU." (PMID 37268997, 2023). "We have found that abnormal expression of EZH2 can be detected in various cancer tissues." (PMID 37198697, 2023). "EZH2, a key molecule highlighted in recent research, is of great value in the field of cancer." (PMID 36724065, 2023). "EZH2 is essential for the proliferation and metastasis of cancer." (PMID 37069494, 2023). "In cancer, EZH2 induces epithelial–mesenchymal transition (EMT), which is relevant in metastasis." (PMID 36768289, 2023). "Finally, lncRNA DANCR showed the ability to support EMT, cancer stemness, and inflammation in BC cells in vitro by promoting the binding of EZH2 to the SOCS3 promoter, thereby inhibiting its expression." (PMID 37275549, 2023). "EZH2 hypertrimethylation of histone H3 lysine 27 (H3K27) leads to cancer cell de-differentiation." (PMID 37772080, 2023). "Highly expressed EZH2 is indicative of unsatisfactory prognoses for NSCLC, which may be associated with cancer phases or carcinoma types." (PMID 37069494, 2023). "In general, the important role of EZH2 in cancer is the focus of much research." (PMID 37268997, 2023). "Therefore, EZH2 plays a critical oncogenic role in numerous related processes including cancer initiation, differentiation, development, progression, and metastasis." (PMID 36759799, 2023). "It is noteworthy that miR-138-5p and EZH2 are hot subjects in cancer research." (PMID 36901978, 2023). "EZH2 has been shown to have an oncogenic role in cancer development and progression." (PMID 37941056, 2023). "Besides circSAMD4A, miR-138-5p is also targeted by lncHCP5, lncSNHG7 and lncDSCAM-AS1 in promoting tumor growth in various cancers, all of which also act through EZH2." (PMID 36901978, 2023). "EZH2 is a known marker for the progression of different types of cancers." (PMID 37862362, 2023). "Interestingly, in the context of its epigenetic role, studies have confirmed that CHD4 can interact with the methylation enzymes DNMT1, DNMT3B, EZH2 and G9a in cancer progression." (PMID 36681835, 2023).
cancer (continued). "However, cancer cells generate resistance to these drugs by using driver genes such as Myc and EZH2 to increase Top2 catalytic function and DNA damage repair (DDR) machinery, thus overcoming replication and transcription stress and avoiding cell death." (PMID 36678591, 2023). "EZH2 exerts its cancer-promoting role by promoting T-cell senescence and immune evasion." (PMID 37268997, 2023). "The enzymatic inhibition of EZH2 has been intensively studied as a therapeutic strategy in cancer." (PMID 36627707, 2023). "First, the expression of EZH2 in pan-cancer (18 malignancies) was analyzed with the TCGA database." (PMID 37626362, 2023). "Additionally, EZH2 can cooperate with BRCA1 to maintain a cancer stem cell signature, promoting radioresistance." (PMID 37455903, 2023). "EZH2 inhibitors are currently being evaluated in clinical trials, such as a phase 1/2 study, using the combination of tazemetostat and pembrolizumab, involving multiple types of cancers, including HNSCC." (PMID 38136558, 2023). "Thus, the molecular features of EZH2 genetic alterations, DNA methylation, and protein phosphorylation were comprehensively detected and explored based on the TCGA pan-cancer cohort." (PMID 36545914, 2023). "Next, we will introduce the mechanism of EZH2 in cancer in different ways." (PMID 36672374, 2023). "Up regulation in primary cells may be explained by many findings that some polycomb mechanism genes have independent functions from their PRC(s) in many cancers, such as cell cycle progression roles, as discussed for EZH2." (PMID 36809239, 2023). "Enhancer of zeste homolog 2 (EZH2) was upregulated in several types of human cancers." (PMID 36968022, 2023). "Therefore, targeting EZH2 for cancer treatment is now a popular area of research, and several EZH2 inhibitors have been developed." (PMID 36678591, 2023). "Therefore, in this review, we first introduce EZH2 and clarify the mechanisms of abnormal expression of EZH2 in cancer." (PMID 36672374, 2023). "These PcG complexes are typically used to interact directly with DNMTs and may aid in the silencing of cancer-specific proteins such as enhancer of zeste homolog 2 (EZH2)." (PMID 37107631, 2023). "Besides its role in embryonic development, aberrant PRC2 and EZH2 activity has been described in several human cancer types." (PMID 36900361, 2023). "EZH2 in cancer cells downregulates NKG2D ligand expression or TME and inhibits NK cell activation." (PMID 37909018, 2023). "Accordingly, by using an MCS model consisting of human MPM cells and monocytes, we have demonstrated that tazemetostat enhances both the recruitment and M2-polarized activation of monocytes, blocking the anti-proliferative effects of EZH2 inhibition in cancer cells." (PMID 36900330, 2023). "Finally, quantitative reverse transcription polymerase chain reaction and immunohistochemical assays were performed to verify the differential expression of EZH2 gene in various cancers at the mRNA and protein levels." (PMID 36545914, 2023). "Both TMPRSS2-ERG and EZH2 are included in the Catalogue of Somatic Mutations in Cancer, however the whole-genome sequencing of PCa did not designate these genes as cancer drivers." (PMID 36769153, 2023). "The findings suggest that targeting PRC2, such as using an EZH2 inhibitor, could be a promising approach for developing anti‐cancer drugs for CCA." (PMID 38050190, 2023). "Additionally, EZH2 expression was correlated with clinical prognosis, and its up-regulation usually indicated poor survival outcomes in cancer patients." (PMID 36545914, 2023). "Furthermore, numerous bioinformatics analysis databases also reapplied to comprehensively explore and elucidate the oncogenic mechanism and therapeutic potential of EZH2 from pan-cancer insight." (PMID 36545914, 2023). "Our above results suggest that CA has a cancer-inhibiting effect by interfering with EZH2." (PMID 38264522, 2023).